E2F2 (E2F transcription factor 2)
Diseases named in the same sentence as E2F2 in open-access papers (continued):
Sharing a sentence is not in itself a finding about the gene and the disease.
tumor (continued). "It is very likely that E2F2, CDK6, and CDK3 act cooperatively to initiate or promote tumor development and progression." (PMID 26498144, 2016). "We find that in normal samples and superficial tumor samples, the activity for the modules of the E2F1, E2F2 and E2F3 target genes is lower than in invasive tumors, as opposed to the target genes of the inhibitory transcription factors E2F4 and E2F6." (PMID 26925094, 2016). "Analysis of E2F2, CDK1, CDC20, UBE2C and the proliferation biomarker Ki67 in xenograft sections showed consistently lower levels in the shASCT2 tumours." (PMID 25693838, 2015). "Real-time RT-PCR also showed that miR-31 was able to downregulate the expression of E2F2 and STK40 after p21 shRNA treatment, further demonstrating that the tumor-suppressive effects of miR-31 were dependent on reduced p21 expression." (PMID 25568668, 2014). "E2F2 interacts with certain elements in the E2F1 promoter and both genes are involved in DNA replication and repair, cytokinesis, and tumor development." (PMID 20422009, 2010). "Notably, the active E2F2 transcription factor in these stages upregulated UHRF1, enhancing the methylation of tumour suppressor genes." (PMID 40579780, 2025). "The transcription factor network of C3 MKl67+ tumor cells was mainly composed of E2F1, E2F2, etc.." (PMID 40230840, 2025). "Additionally, E2F2, an active transcription factor in the DP and DN stages, upregulates the expression of UHRF1, resulting in hypermethylation of tumor suppressor genes." (PMID 40579780, 2025). "Collectively, our research has established that MATN1‐AS1 could regulate E2F2 expression, therefore promoting EMT and tumour metastasis in ccRCC." (PMID 39999286, 2025). "Compared with the negative control, the overexpression of E2F2 accelerated tumor cell proliferation, while the overexpression of E2F8 inhibited tumor cell proliferation." (PMID 38371373, 2024). "Similarly, Gene Expression Omnibus (GEO) data and TCGA analysis shown that E2F2 mRNA was highly expression in HCC tissue and was significantly correlated with tumor status, histological grade, and clinical stage." (PMID 38807594, 2024). "Compared with the negative control, the knockdown of E2F2 resulted in the significant loss of tumor cell proliferation, while the knockdown of E2F8 increased tumor cell proliferation." (PMID 38371373, 2024). "Disruption of E2F2/NBR1/MHC‐I signaling with shRNAs or blockade with the corresponding antibodies largely abolishes the tumor‐supportive effects of LINC01232 and inhibits tumor growth driven by M2‐type macrophages." (PMID 37097629, 2023). "E2F2 was mainly detected in the cytoplasmic in the normal mucosa and CRC tumor tissues." (PMID 35069909, 2022). "Similarly, a previous study revealed that cell viability and colony formation were reduced after E2F2 expression knockdown in non-small cell lung cancer (NSCLC) cells, indicating that E2F2 acts as an activator in tumor progression of the NSCLC." (PMID 36012128, 2022). "However, further study is needed to determine how the tumor microenvironment is regulated by NELFE and E2F2 or other RNA-binding proteins and to clarify the therapeutic value of these components." (PMID 34295816, 2021). "Compared to normal samples, the expression of E2F2, FOXJ1, EMX1, PAX7, NKX6-1, FOXD1, and ZNF552 was significantly higher (P < 0.05) and the expression of MSX1, STAT4, NR3C2, and EGR3 was significantly lower in tumor samples (all P < 0.05)." (PMID 33688372, 2021).
tumor (continued). "We further discovered that E2F2 is a novel target gene of B-Myb, and B-Myb plays a tumor-promoting role in CRC via mutual collaboration and forming reciprocal feed-forward loops with E2F2, which is essential for the activation of ERK and AKT signaling pathways in CRC." (PMID 34316028, 2021). "Compared with that in adjacent nontumor tissues, the expression level of E2F2 in tumor tissues was higher." (PMID 34295816, 2021). "The expression of E2F2 and KLF5 was more prominent at the edge of the tumor cystic wall." (PMID 35155179, 2021). "The results showed that in the E2F2-knockdown group, no tumor metastases were observed in the lungs of the mice (0/6), while metastases were observed in the lungs of each mouse in the control group (6/6)." (PMID 34295816, 2021). "Specifically, miR-150 negatively regulates forkhead box transcription factor (FOX)-P1, which inhibits the progression of lymphoid malignancies, while miR-31 targets E2F transcription factor 2 (E2F2) and class II PI3 kinases (PIK3C2A) and inhibits tumor cell proliferation in FL." (PMID 33168041, 2020). "In this study, E2F2 expression was found to be higher in OC tissues than in normal tissues and was significantly and negatively correlated with tumor stage in patients with OC." (PMID 30967995, 2019). "E2F2 acts as a tumor suppressor by modulating apoptosis via the suppression of Myc-induced proliferation and tumorigenesis, while TXNIP has been shown to act as a tumor suppressor in thyroid cancer." (PMID 29434270, 2018). "We also found a positive correlation between the expression of E2F2 and EMR2 in human tumours." (PMID 29072692, 2017). "Furthermore, our animal experiments and studies using clinical samples showed an inverse correlation between miR-214 levels and expression of E2F2, CDK3, and CDK6, as well as tumor progression." (PMID 26498144, 2016). "Conversely, metastatic lesions were readily visible in the MMTV-Myc mice lacking E2F2 in 67% of tumor bearing mice." (PMID 26474282, 2015). "However, measurements of motif activity correlation with mRNA expression of the TFs shows that the expression of E2F1, E2F2 and E2F8 exhibit the most significant correlation with E2F motif activity in the time course and tumor studies." (PMID 24464994, 2014). "Despite its well-known positive regulation of cell proliferation, the contribution of E2F2 to tumorigenesis is not so clear, since it has been reported to exert either pro-oncogenic or tumor suppression effects." (PMID 25202354, 2014). "The data indicate that both E2F1 and E2F2 could be highly expressed in tumor tissues correlating with elevated expression of KDM5B (Spearman's rank correlation coefficient: r = 0.666 [E2F1] and r = 0.756 [E2F2], respectively)." (PMID 20226085, 2010). "We also find that distinct types of tumors emerge from the Eμ-myc mice, distinguished by different patterns of gene expression, and that the relative proportions of these tumor types are affected by the absence of either E2F2 or E2F4." (PMID 19749980, 2009). "Whereas the absence of E2F1 and E2F3 function has no impact on Myc-mediated tumor development, the absence of E2F2 substantially accelerates the time of tumor onset." (PMID 19749980, 2009). "LINC01232 binds to E2F2 to enter the nucleus and collaboratively upregulates NBR1, mediating the degradation of histocompatibility complex Class I molecules (MHC-I) by autophagy lysosomes, enabling CD8+ T cells to effectively recognize tumor-specific antigens and thereby evade immune surveillance." (PMID 40585979, 2025). "However, the associations between E2F2 mRNA expression and T stage, gender, age, CEA level, residual tumor, perineural invasion, lymphatic invasion, colon polyps present and tumor location were not statistically significant (all p > 0.05)." (PMID 35069909, 2022).
tumor (continued). "Importantly, E2F1, E2F2 and E2F8, previously identified as strong candidate regulators of early PB-mediated transient hyperplastic response, display similar positive correlation between their gene expression and the motif activity in the tumor." (PMID 24464994, 2014). "Moreover, we also found higher expression levels of both E2F1 and E2F2 in clinical tumor tissues where KDM5B was overexpressed, than in non-neoplastic tissues (P = 0.0009 and P = 0.0002, respectively)." (PMID 20226085, 2010). "Therefore, PLAG2A, E2F2 and CDC42 are the primary candidate tumor suppressors in this region." (PMID 16982006, 2006). "In this study, pBD2 showed anti-tumor potential by upregulating the expression of PTEN and downregulating the expression of SPRY2 and PLAU, and pBD2 was also shown to promote cell proliferation by upregulating the expression of CDC25A, E2F2, and PTGS2, which perhaps might lead to tumorigenesis." (PMID 36077151, 2022). "The E2F2 expression in LGG showed a positive correlation with infiltrating levels of B cells, CD4+ T cells, macrophages, neutrophils, and dendritic cells but not with tumor purity." (PMID 33381564, 2020). "Furthermore, Exo exerted no influence on E2F2, PI3K and Akt in tumor tissues." (PMID 35353027, 2022).
cancer (112 papers, 2010 to 2025). A tumor composed of atypical neoplastic, often pleomorphic cells that invade other tissues. "In humans, the E2F2 gene is located on chromosome 1p36.13, and mutations in this gene have been associated with various types of cancer." (PMID 38807594, 2024). "In cancer, overexpression of E2F2 has been found in various types of cancer, and the abnormal expression of E2F2 is often associated with the occurrence, metastasis and recurrence of tumors." (PMID 38807594, 2024). "We corroborated these findings by validating the expression of their key candidate markers: HK1, which regulates glycolysis, and the E2F2 transcription factor associated with key cancer pathways." (PMID 35626705, 2022). "Some studies showed that E2F Transcription Factor 2 (E2F2) promoter polymorphisms, which affect the expression of E2F2, are significantly associated with increased risk of many cancers." (PMID 33860054, 2021). "E2F2, another important family member of E2F, is also involved in regulating the cell cycle and is associated with cancer growth." (PMID 29357938, 2018). "Previous studies demonstrated that altered expression of E2F2 protein was closely associated with development of different cancers." (PMID 27174918, 2016). "As an emerging initiator for carcinogenesis, aberrant E2F2 expression has been reported to be associated with cancer progression and metastasis." (PMID 26967247, 2016). "Similarly, E2F2 is crucial for transcribing genes necessary for S-phase entry, and its downregulation has been linked to decreased proliferation and increased apoptosis in various cancer models." (PMID 41008631, 2025). "E2F2 is ubiquitously expressed in mammalian tissues, with high levels detected in proliferating cells such as embryonic tissues and cancer cells." (PMID 38807594, 2024). "Here, we summarize several strategies that have been used to either alter or utilize E2F2 activity in preclinical settings to target cancer cells." (PMID 38807594, 2024). "E2F2, on the other hand, has been shown to have a suppressive effect on cell proliferation and to promote apoptosis in specific cancer types." (PMID 38360622, 2024). "Proliferative cancer cells specifically express TFs involved in cell proliferation, including E2F TF family members (E2F2, E2F8, and E2F7)." (PMID 37853464, 2023). "Notebally, it has been poorly described for the role of E2F2 in gene instability and repair in the context of cancer until now." (PMID 35069909, 2022). "E2F2 was up-regulated in PCa in comparison to the benign tissue (benign vs. cancer = 0.19 ± 0.03 vs. 0.35 ± 0.01, p < 0.01)." (PMID 35531101, 2022). "To determine the overall expression levels of E2F2 in different malignances, we firstly analyzed E2F2 expression across different cancer types using TIMER database." (PMID 35069909, 2022). "The results illustrated that E2F2 exhibited divergence in expression profiles among various cancers." (PMID 35069909, 2022). "Our present findings are in accordance with previous observations describing the oncogenic role of E2F2 in other cancers." (PMID 35844795, 2022). "Our study elucidated the role of NORAD in cancer cell proliferation, invasion, and migration of LC with the involvement of the miR-28-3p/E2F2 ceRNA network." (PMID 36245705, 2022). "Reinforcing this view, knockdown of E2F2 in a different experimental setting (a cancer-derived human cell line) leads to FAS promoter activation and transcription." (PMID 35008734, 2021). "Overexpression of CDK1, MCM2, E2F2, PLK1, CCNB1/2, BUB1, BUB1B, CDC25 has been associated with aberrant proliferation in many cancer types including HCC." (PMID 33499054, 2021).
cancer (continued). "This global approach further highlighted strong correlations between A3B and expression of E2F1, E2F2, E2F7, and E2F8 and indicated that the association between A3B, this signal transduction pathway, and the cell cycle is evident in many cancer types." (PMID 30723127, 2019). "E2F2 was critical to many cell processes, including the cell cycle, proliferation, differentiation and cancer development." (PMID 30487158, 2018). "At the mRNA level, E2F2 expression was significantly downregulated in ccRCC cancer tissues compared with normal tissues (P < 0.001)." (PMID 26967247, 2016). "Comprehensive studies indicate that E2F2 plays a critical role in miR-155-regulated cancer cell proliferation and invasion." (PMID 26967247, 2016). "E2F2 is involved in the control of the G1/S phase transition and S phase progression and its overexpression has been described in many cancers, in which it is thought to promote cell proliferation." (PMID 26322309, 2015). "Accordingly, overexpression of CCND2, E2F1 and E2F2 were reported in various cancer types, including OS." (PMID 25174983, 2014). "We confirmed the down-regulation of E2F1 and E2F2 expression in three different cancer cell lines, SW780, A549 and SBC5 treated with siRNAs, by quantitative real-time PCR." (PMID 20226085, 2010). "Notably, the MYC, E2F2 and CASP8 genes, which are important regulators of the cell cycle and apoptosis and have previously been implicated in HPV-related processes or cancer, were identified as common trans-interaction sites in both the HiC and 4C datasets." (PMID 40892869, 2025). "While overexpressing E2F2 in cancer cells displayed an opposite function." (PMID 39999286, 2025). "However, genome instability in cancer cells ultimately leads to a dysregulation of E2F2-dependent transcription." (PMID 36547888, 2022). "Importantly, we found that the expression of E2F2, which is known to be dysregulated in various cancers, was significantly related to DLEU2 expression." (PMID 35075115, 2022). "The results above demonstrated that E2F2 could be involved in cancer initiation and progression for CRC patients." (PMID 35069909, 2022). "Similarly, E2F2 is upregulated and promotes the malignant activities of cancer cells in pancreatic cancer and osteosarcoma." (PMID 35075115, 2022). "Multiple studies have reported the function of E2F2 in modulating cancer PI3K/Akt signaling." (PMID 35353027, 2022). "Moreover, multicancer invasiveness signature and cancer stem cells were significantly enriched in low E2F2 expression group." (PMID 35069909, 2022). "In our present study, we found that E2F2 mRNA expression varied across different types of cancers." (PMID 35069909, 2022). "Similarly, miR-155 is involved in numerous cancer types and its upregulation in ccRCC correlates with an increase in proliferation and invasion by targeting Forkhead box O3a (FOXO3a) and E2F transcription factor 2 (E2F2)." (PMID 33918154, 2021). "E2F Transcription Factor 2 (E2F2) could contribute to cancer development, because it plays a critical role in many cellular processes, including the cell cycle, proliferation, differentiation, DNA damage response, and cell death." (PMID 33860054, 2021). "However, E2F2 is lost in most of the cancers, sequentially leading to uncontrolled cell cycle progression." (PMID 32752229, 2020). "E2F2, like E2F1, can play a dual role in suppressing and causing cancer." (PMID 33604289, 2020). "Taken together this manuscript defines a novel role of E2F2 in cancer progression beyond cell cycle and could impact patient treatment." (PMID 33087787, 2020). "E2F2 expression is positively correlated with ANCCA/PRO2000 in cancer cells." (PMID 27239961, 2016).